BCL2 (BCL2 apoptosis regulator)
Diseases named in the same sentence as BCL2 in open-access papers (continued):
Sharing a sentence is not in itself a finding about the gene and the disease.
cardiovascular disease (19 papers, 2013 to 2025). "As a classical pathogenic mechanism of a variety of cardiovascular diseases, stress-induced cardiomyocyte apoptosis has been proved to be related to the reduction of anti-apoptotic Bcl-2 and the increase in pro-apoptotic Bax and cleaved caspase-3 via activing the Wnt/β-catenin pathway." (PMID 32138681, 2020). "Several lncRNA–mRNA regulatory axes are involved in the action mechanisms of MSC-Exos in cardiovascular diseases, such as KLF3-AS1/sirtuin 1 (SIRT1), MALAT1/autophagy-related 4a (ATG4a), urothelial cancer associated 1 (UCA1)-Bcl-2, and Mir9-3hg/Pum2." (PMID 38812041, 2024). "Cardiovascular diseases significantly impact blood pressure levels, and BCL2, a key anti-apoptotic protein, can serve as a target for modern cardioprotective therapies." (PMID 39272451, 2024). "MicroRNA‐499 (miR‐499), microRNA‐208a (miR‐208a) and B‐cell lymphoma 2 (Bcl‐2) play roles in cardiovascular diseases, such as direct reprogramming of cardiac fibroblast into cardiomyocyte and cardiomyocyte apoptosis." (PMID 33605072, 2021). "Apoptotic proteins (caspase 3, Bcl-2, and Bax) also play an essential role in the onset of cardiovascular diseases." (PMID 33312223, 2020). "In this study, pathway enrichment analysis showing the presence of NFKB1 and BCL2 in module 1 indicated a particular association with the NF-κB signalling pathway, indicating that NFKB1 and BCL2 may be correlated with the effects of DSSM against cardiovascular diseases through this pathway." (PMID 29348768, 2017). "The results showed TFDM was the main active ingredient in DML and could exert therapeutic effects on cardiovascular diseases through the NOX-4/ROS/p38 MAPK, Bcl-2/Bax and AMPK/SIRT1/PGC-1α signalling pathways." (PMID 38169375, 2024). "Thus, DSSM exerts effects against cardiovascular diseases by targeting JUN, TNF, NFKB1, FOS, and BCL2." (PMID 29348768, 2017). "Studies are still uncovering BCL-2 proteins’ non-apoptotic functions in metabolism, mitochondrial dynamics, and immunity, which may reveal their roles in neurodegeneration, autoimmune, and cardiovascular disorders." (PMID 40204952, 2025).
neurological diseases (19 papers, 2010 to 2025). "As a signaling pathway that regulates cell apoptosis and survival, the Bcl-2/Bax/cleaved caspase-3 apoptotic signaling pathway has been implicated in many diseases including several nervous system diseases." (PMID 38033740, 2023). "Bcl2 family-related proteins [Bcl2, Bcl-xL (also known as Bcl2l1), Bax and Bak1] play an essential role in the neuronal apoptotic pathway in various neurological diseases." (PMID 32540990, 2020). "In CR, 52 AD-related target proteins were validated to bind with 25 active ingredients, including ACHE, APP, BCHE, BCL2, BAX, CASP3, and CASP7, and are implicated in cell apoptosis and vascular and nervous system diseases." (PMID 32802132, 2020). "Recent studies have also shown that BM extract downregulates Bax and upregulates Bcl2 and thus provides neuroprotection in several neurological disease models." (PMID 26413124, 2015). "Our findings revealed a significant reduction in BCL2 gene expression and protein levels, and a notable increase in BAX levels, indicating an imbalance that likely contributed to the enhanced neuronal cell death associated with this neurological disorder." (PMID 41523603, 2025). "Bcl-2/Bax/cleaved caspase-3 apoptosis signal is a signaling pathway that regulates cell apoptosis and survival, which is related to a variety of diseases including nervous system diseases." (PMID 35287689, 2022). "Bcl-2/Bax/caspase-3 apoptosis signalling is a crucial regulator in cell survival and apoptosis, and targeting this pathway is considered as a potential strategy to reduce the apoptosis of neurons in a variety of neurological diseases." (PMID 33550883, 2021). "Notably, edaravone, a free radical scavenger drug currently in clinical trials for various neurological disorders, has been shown to be neuroprotective by enhancing expression of BDNF, Bcl-2 and suppressing caspase-3 activity." (PMID 26016641, 2015). "Acupuncture treats nervous system diseases by increasing the brain-derived neurotrophic factor level and involves multiple signal pathways, including p38 MAPKs, Raf/MAPK/ERK 1/2, TLR4/ERK, PI3K/AKT, AC/cAMP/PKA, ASK1-JNK/p38, and downstream CREB, JNK, m-TOR, NF-κB, and Bcl-2/Bax balance." (PMID 31379957, 2019).
bacterial infection (11 papers, 2015 to 2025). "Studies with the intracellular pathogen Coxiella burnetti have demonstrated that this pathogen may modulate autophagy as well as apoptosis pathways through BECN1/BCL2 interplay modification to generate a persistent bacterial infection in the host cells." (PMID 28056107, 2017). "Thus, Bcl2AAA epithelial cells are unable to phosphorylate BCL2 in response to bacterial infection." (PMID 39602254, 2024). "Investigations on bcl2 marker in gingival cells during periodontal inflammation we suggestion that periodontium tissues, continuously exposed to bacterial infections may contain cells with high level of myeloperoxidase results that damage DNA by product of catalysis." (PMID 26251029, 2015). "Whereas Class2 uniquely included pathways related to bacterial infections (e.g., E. coli, Salmonella) together with actin-cytoskeleton and T-cell modules (e.g., ACTB, PFN1, RAC2, PIK3CD, CD3D/CD3G, STING1, TRADD, CASP8, BCL2, HLA-F)." (PMID 41394852, 2025). "The basic attention is devoted to the immune-modulating activity of TDNG following exposure to the bacterial infection (P. putida) which is indicated by augmenting levels of C3 and LYZ plus up-regulation of the response of the BCL-2 and down-regulation of caspase-3." (PMID 38561720, 2024). "Clearly, nicotine has an important role in promoting cellular survival in macrophages regardless of bacterial infection by increasing the expression of Bcl2." (PMID 34070119, 2021).
inflammation (9 papers, 2015 to 2025). Aberrant reaction of the microcirculation characterized by movement of fluid and leukocytes from the blood into extravascular tissues. "We show that female mice express reduced Bcl-2 mRNA and protein levels, and this may explain why they are more susceptible to lung inflammation." (PMID 38113109, 2023). "In conclusion, our results demonstrated that glucocorticoids ameliorated PM-induced lung inflammation by scavenging ROS, decreasing mitochondrial dysfunction, and restoring Bcl-2/GR complex formation in a GR-dependent manner." (PMID 37919369, 2023). "Bcl-2 expression mediates LPS-induced neutrophilic inflammation and chronic airway inflammation, suggesting that Bcl-2 may have a role in LPS-induced neuroinflammation." (PMID 35742844, 2022). "Regarding GIP agonists (D-Ala2-GIP-glu-PAL), neuroprotection in MPTP-treated rats and cell cultures was confirmed through the reduction in dopaminergic neurons and an increase in the antiapoptotic protein Bcl-2 (β-cell lymphoma 2), which prevented apoptosis and reduced chronic brain inflammation." (PMID 31871617, 2019). "It has been reported that hispolon suppressed Bcl-2 protein expression and increased Bax and caspase-3 protein expression, resulting in the inhibition of severe ER stress and limiting the lung injury triggered by lung cell apoptosis and lung inflammation in ALI mice induced by LPS." (PMID 36998049, 2023). "Finally, we found that ABT199 attenuated PM-induced lung inflammation via inhibiting Bcl-2." (PMID 29944468, 2018).
cardiac disease (5 papers, 2011 to 2025). "The different cAMP/cGMP ratio observed after Sildenafil treatment in Pde5a+/+ mice under the two TAC conditions, seems to correlate with increased phosphorylation of ERK1/2 kinases and up-regulation of Bcl2 as previously reported in another cardiac disease model." (PMID 40659490, 2025). "Since BCL-2 is a well-known anti-apoptotic protein, BCL-2 regulation in cardiac disease may be instrumental to react to or compensate for inflammatory or oxidative stress." (PMID 28666417, 2017). "These previous studies and our results suggest that the protein levels of apoptotic-related factors such as BCL2 and BAX may play a vital role in the initiation and development of cardiac disease in DRM." (PMID 21541347, 2011). "However, non-IFN-γ synthesizers had lower STAT-5 phosphorylation, less IL-7 receptor functionality, and reduced CD25 regulation (mainly in those with severe heart disease) in CD4+ T cells, accompanied by lower Bcl-2 expression in TCD4+ and TCD8+ cells after IL-7 stimulation." (PMID 39907396, 2025).
infectious disease (5 papers, 2010 to 2023). A disorder directly resulting from the presence and activity of a microbial, viral, or parasitic agent in humans. "We also noticed that apoptosis-related pathways (2 hypermethylation and 4 hypomethylation genes) including B cell leukemia/lymphoma 2 (Bcl2) and interleukin-1 receptor-associated kinase 1 (Irak1) and infectious disease were involved." (PMID 34884879, 2021). "B cell lymphoma 2 (Bcl-2) family proteins play important roles in regulating apoptosis during homeostasis, tissue development, and infectious diseases." (PMID 32161176, 2020). "IMPORTANCE B cell lymphoma 2 (Bcl-2) family proteins play important roles in regulating apoptosis during homeostasis, tissue development, and infectious diseases." (PMID 32161176, 2020). "This is the first report that demonstrates in an infectious disease model that lack of both IL-7 and IL-15 not only down-regulates the development of CD127hi subset, but also reduces the frequency of CD127hi cells expressing Bcl-2." (PMID 20520779, 2010).
benign tumors (4 papers, 2009 to 2024). "While 100% (2/2) of the normal specimens were found to have a positive Bcl-2 staining in more than 50% of the stromal cells, 35% (6/17) of benign tumors had Bcl-2 expression in more than 50% of the stromal cells." (PMID 19852858, 2009).
myopathy (4 papers, 2016 to 2021). A disease of the muscle in which the muscle fibers do not function properly. "Consistently, WB myopathy increased the protein contents of Cytc and caspase 3, but decreased the Bcl-2 protein content in comparison with the CON group (P < 0.05)." (PMID 33935806, 2021). "There was a lower proportion of fibres expressing Bcl-2 in the two groups with inflammatory myopathies compared to controls." (PMID 32936839, 2020). "Evidence for this shown here for the first time includes: enhanced Annexin positive cell percentage, reduced mitochondrial potential membrane, increased pro-apoptotic Bax expression levels and decreased anti-apoptotic Bcl-2 protein levels in GNE myopathy myoblasts." (PMID 26968811, 2016).
psychiatric disorder (4 papers, 2009 to 2020). A disorder characterized by behavioral and/or psychological abnormalities, often accompanied by physical symptoms. "A level of 0.35 mM has been reported to robustly increase Bcl2 in rat brain, levels of 0.1 to 0.2 mM are neuroprotective against glutamate toxicity, and 0.4 to 1.25 mM is considered a safe and effective concentration range for human use in psychiatric disorders." (PMID 19649300, 2009).
retinopathy (3 papers, 2021 to 2023). "Meanwhile, they reduced the expression of VEGF and ICAM1 in retinopathy and increased the expression of Bcl-2 and PEDF." (PMID 34691233, 2021). "The degree of retinopathy was evaluated by staining retinal sections with hematoxylin and eosin, and the expression of CCN1, HIF-1α, VEGF, caspase-3, Bcl-2, IL-1β, and TNF-α protein was analyzed by Western blotting and immunohistochemistry." (PMID 35445044, 2022).
CNS tumors (2 papers, 2024). "Potential targets for CNS tumors include Vascular Endothelial Growth Factor (VEGF), Bcl2, Stat3 and many immune related targets." (PMID 38348876, 2024).
gastrointestinal disease (2 papers, 2021 to 2025). A disease that occurs in the gastrointestinal system, excluding the hepatobiliary system. "This integrated approach not only broadens our understanding of BCL2 inhibitors in gastrointestinal diseases but also highlights their promise in reshaping therapeutic options for AP." (PMID 40715042, 2025).
neoplastic disorders (2 papers, 2008 to 2022). "However, Bcl-2 expression is increased when cell proliferation in tissues is dysregulated in hyperplastic and neoplastic disorders." (PMID 18652667, 2008). "In fact, the early expression of Bcl-2 in feline inflammatory enteropathy suggests a transition between inflammatory and neoplastic disorders, but this has not been proven." (PMID 35448666, 2022).
animal disease (1 paper, 2022). "In several animal disease models, H2S decreased the expression of pro-apoptotic caspases, increasing the expression of anti-apoptotic mediators, such as Bcl-2." (PMID 35628328, 2022).
BCL2 also shares sentences with these, for which no sentence is quoted: breast (15 papers); acute myocardial infarction (12); gastrointestinal tumors (7); Parkinson (7); metabolic disorders (6); Immunodeficiency (5); chronic periodontitis (4); digestive system cancer (4); idiopathic pulmonary fibrosis (4); malnutrition (4); metastasis (4); multiple sclerosis (4); odontogenic keratocysts (4); renal failure (4); schwannoma (4); urothelial carcinoma (4); anaplastic astrocytoma (3); autoimmune thyroid disease (3); buccal mucosa cancer (3); cutaneous squamous cell carcinoma (3); experimental autoimmune encephalomyelitis (3); intrahepatic cholestasis (3); kidney tumors (3); lipid metabolism disorder (3); lymphoplasmacytic lymphoma (3); medullary thyroid carcinoma (3); smooth muscle tumor (3); allergic dermatitis (2); angina (2); Ascites (2).
A further 239 diseases each share a sentence with BCL2 in 2 papers or fewer.